JUP (junction plakoglobin)
Diseases named in the same sentence as JUP in open-access papers (continued):
Sharing a sentence is not in itself a finding about the gene and the disease.
colon carcinoma (2 papers, 2023). "Here, we demonstrated that miR-195-5p was downregulated in colon cancer tissues, while JUP was overexpressed in CRC tissues compared to the normal counterpart." (PMID 38203664, 2023). "In this study, using a public data repository, we reported that miR-195-5p was downregulated in colon cancer tissues; inversely, JUP mRNA expression was found to be increased in CRC patients compared with normal counterpart tissues." (PMID 38069408, 2023). "Interestingly, in colon cancer cell lines, we found that increasing intracellular miR-195-5p was able to reduce the protein expression levels of NLK, LEF1 and Cyclin D1 via JUP modulation." (PMID 38069408, 2023).
dilated cardiomyopathy (2 papers, 2020 to 2023). Cardiomyopathy which is characterized by dilation and contractile dysfunction of the left and right ventricles. "For example, mutations in JUP, DSP, PKP2, DSG2, DSC2, CTNNA3, CDH2, or PLN (all of them more abundant in LV) predominantly lead to arrhythmogenic right ventricular cardiomyopathy, and mutations in MYH7, HSPB7, NEXN and MYPN (also all more abundant in LV) lead to dilated cardiomyopathy." (PMID 32291283, 2020).
epithelial ovarian cancer (2 papers, 2020 to 2024). "It is conceivable that a similar process exists for ovarian cancer, where upregulation of JUP contributes to the formation of ovarian cancer cell aggregates known as spheroids, promoting the release of cancer cells into the abdominal cavity." (PMID 33102207, 2020). "Our strategy resulted in the identification of a promising new marker for epithelial ovarian cancer, junction plakoglobin (JUP, plakoglobin, γ-catenin)." (PMID 33102207, 2020).
gastric cancer (2 papers, 2018 to 2021). A primary or metastatic malignant neoplasm involving the stomach. "We screened out five overlapping Shc1-binding proteins (JUP, EPHA2, RASAL2, LYN, and SHCBP1), which were positively correlated with HER2 expression and were upregulated in gastric cancer." (PMID 33990570, 2021).
heart failure (2 papers, 2019 to 2024). Inability of the heart to pump blood at an adequate rate to meet tissue metabolic requirements. "In the heart, the SPTBN2 and JUP have established roles in mechanical function, and alterations in these proteins are associated with heart failure and cardiomyopathy." (PMID 31792287, 2019). "This study demonstrates that Mycn activates USP2 transcription, which mediates ubiquitination and protein stabilization of JUP, thus inactivating the Akt/β-catenin axis and alleviating cardiac hypertrophy-induced heart failure." (PMID 38297207, 2024).
Parkinson disease (2 papers, 2022 to 2025). A progressive degenerative disorder of the central nervous system characterized by loss of dopamine producing neurons in the substantia nigra and the presence of Lewy bodies in the substantia nigra and locus coeruleus. "Similarly, Junction Plakoglobin (JUP), which has the double role of hub and bottleneck, has been associated with Parkinson’s disease initiation." (PMID 40194557, 2025).
Right ventricular cardiomyopathy (2 papers, 2012 to 2020). Right ventricular dysfunction (global or regional) with functional and morphological right ventricular abnormalities, with or without left ventricular disease. "The essential physiological role of JUP for regular function of desmosomes in the myocardium is indicated by the findings of premature cardiac death of JUP knockout mice and arrhytmogenic right ventricular cardiomyopathy in patients carrying mutations in the JUP gene." (PMID 23110151, 2012).
Stroke (2 papers, 2015 to 2023). Sudden impairment of blood flow to a part of the brain due to occlusion or rupture of an artery to the brain. "In the future, significant proteins including UBC, CUL3, APP, NEDD8, JUP, SIRT7, etc., can be potent drug targets for first aid and emergency treatment within 24 h post-stroke." (PMID 26679092, 2015).
Alzheimer disease (1 paper, 2025). A progressive, neurodegenerative disease characterized by loss of function and death of nerve cells in several areas of the brain leading to loss of cognitive function such as memory and language. "We identified four proteins (DSP, JUP, HRNR, and DDX6) that bind to amyloid‐beta (Aβ) oligomers derived from the brains of Alzheimer's disease (AD) patients." (PMID 40276647, 2025).
atherosclerosis (1 paper, 2012). A disease characterized by the build-up of fatty material and calcium deposition in the arterial wall resulting in partial or complete occlusion of the arterial lumen. "In conclusion, this is the first report of JUP and its isoforms in the context of atherosclerosis and cardiovascular disease." (PMID 23110151, 2012).
cardiac hypertrophy (1 paper, 2024). "We hypothesized that USP2 possibly mediates JUP deubiquitination and inactivates the Akt/β-catenin cascade to ameliorate cardiac hypertrophy." (PMID 38297207, 2024). "Collectively, we hypothesized that Mycn possibly regulates USP2 transcription, which modulates JUP protein stability and the Akt/β-catenin signaling to affect cardiac hypertrophy progression." (PMID 38297207, 2024).
cardiocutaneous syndrome (1 paper, 2022). "The reported variants associated with cardiocutaneous syndrome, in genes DSP, JUP, DSC2, KLHL24, GJA1, are classified by interpretation guidelines from the American College of Medical Genetics and Genomics." (PMID 36142674, 2022).
chordoma (1 paper, 2013). Chordomas are rare malignant tumors arising from embryonic remnants of the notochord in axial skeleton. "By comparing methylation patterns of blood from healthy individuals and chordoma patients we found 20 significantly differentially methylated genes; 15 hypermethylated in chordoma (for example RASSF1, KL, RARB, HIC1, and FMR1) and 5 hypomethylated (HSD17B4, BAZIA, STAT1, NEUROGL, and JUP)." (PMID 23533570, 2013).
endometriosis (1 paper, 2024). The growth of functional endometrial tissue in anatomic sites outside the uterine body. "We also investigated whether JUP, the protein encoded by the major identified DEG, is secreted by immune cells and detectable in the serum, and whether it could be used as a valuable biomarker for endometriosis." (PMID 39684780, 2024).
Harlequin ichthyosis (1 paper, 2022). Harlequin ichthyosis (HI) is the most severe variant of autosomal recessive congenital ichthyosis (ARCI; see this term). "Interestingly, some of these genes, i.e. KRT1, KRT9, KRT16, DSG1, DSC2 and JUP, are mutated in hereditary PPKs, while the ABCA12 gene is defective in harlequin ichthyosis characterized by the loss of the skin lipid barrier." (PMID 35854363, 2022).
metastatic melanoma (1 paper, 2018). A melanoma that has spread from its primary site to another anatomic site. "Our study found that genes involved in the biological processes of desmosome organization (GO: 0002934) and hemidesmosome assembly (GO: 00031581) in metastatic melanomas, including JUP, PKP3, KRT14, and KRT5, were inhibited." (PMID 29377892, 2018).
myocardial infarction (1 paper, 2012). Gross necrosis of the myocardium, as a result of interruption of the blood supply to the area, as in coronary thrombosis. "In addition, JUP isoforms could be detected in plasma from patients with PAOD (having peripheral atherosclerotic plaques without suffering a myocardial infarction), but not in a swine model in which non-atherosclerotic myocardial infarction was induced by ligation." (PMID 23110151, 2012).
nephrolithiasis (1 paper, 2024). The presence of a calculus in the pelvis of the kidney; this is most often composed of mineral salts and proteins. "Differential expression of AXL, HIP1R, JUP, CTNNB1, and DSG2 was confirmed via PRM, suggesting their potential roles in the development and advancement of nephrolithiasis, warranting further exploration." (PMID 39114033, 2024).
oral squamous cell carcinoma (1 paper, 2021). "JUP is expressed within intercellular junctions and desmosomes, critical for cell adhesion, and has been shown to promote metastasis in oral squamous cell carcinoma." (PMID 34066295, 2021).
prostate tumors (1 paper, 2022). "We found that GOLPH3 and JUP expression was significantly increased in primary prostate tumors compared to NAT." (PMID 36387263, 2022). "Only two of the three target genes, GOLPH and JUP were significantly increased in primary prostate tumors compared to NAT." (PMID 36387263, 2022). "Attenuation of hsa-miR-133a-3p and miR-1-3p expression by promoter methylation in prostate tumors may enhance PCa development, in part by targeting GOLPH3 and JUP." (PMID 36387263, 2022).
urothelial carcinoma (1 paper, 2021). A malignant neoplasm derived from the transitional epithelium of the urinary tract (urinary bladder, ureter, urethra, or renal pelvis). "Expression of JUP in normal urothelial tissue and urothelial carcinoma, ITGB4 in normal urothelial tissue and urothelial carcinoma were also shown." (PMID 34402716, 2021).
tumor (42 papers, 2006 to 2025). "Taken together, TRIM55 suppresses tumor growth, migration, and glycolysis by mediating K63-linked ubiquitination of JUP and PGK1, inhibiting the MYC pathway and glycolytic activity." (PMID 39768197, 2024). "JUP (junctional plakoglobin or gamma-catenin) associates with cytoplasmic domains of cadherins and has tumor and metastasis suppressor activity." (PMID 26474785, 2015). "Interestingly, we also observed increased expression of KLF10 and JUP, genes typically associated with tumor-suppressive activity and cell-cell adhesion, respectively." (PMID 40950184, 2025). "Here, loss of JUP, presumably contributing to reduced tumor cell cohesion by disturbing desmosome and adherens junction assembly, might additionally promote the more metastasis‐prone phenotype of CHD1‐deleted cancers within the ERG‐negative subset." (PMID 33533127, 2021). "Although JUP has been described as a tumor suppressor, inhibiting OC cell growth, migration, and invasion, its precise role remains under investigation." (PMID 40539060, 2025). "It is worth noting that in ccRCC, JUP shows characteristic low expression, and functional experiments have confirmed that its knockdown promotes tumor occurrence and development, while overexpression significantly inhibits the malignant phenotype of tumors." (PMID 41487520, 2025). "Mechanistically, TRIM50 inhibited tumor development by targeting junction plakoglobin (JUP), a transcription factor, for degradation mediated by K63-linked ubiquitination at the K57 site." (PMID 39768197, 2024). "JUP downregulation or knockdown has been shown to suppress cell aggregation and tumor metastasis formation." (PMID 38203664, 2023). "Together, the results suggest that JUP/AGR2/LYPD3 signaling plays a role in maintaining tumor cell stemness and enhances the glycolytic phenotype." (PMID 37924160, 2023). "We first demonstrated in vivo that upregulation of JUP levels significantly increased tumor growth rate and weight compared to controls, and that this effect was partially reversed by sh-LYPD3 (P < 0.05)." (PMID 37924160, 2023). "Numerous studies found JUP to have properties of a tumor and metastasis suppressor in vivo, but overexpression of JUP caused oncogenic activity in vitro." (PMID 33533127, 2021). "Both oncogenic and tumor suppressor functions have been described for junction plakoglobin (JUP), also known as γ‐catenin." (PMID 33533127, 2021). "Junction plakoglobin (JUP) was found to be elevated in venous blood from ovaries with malignancies when compared to those with benign disease." (PMID 33102207, 2020). "EPPK1 overexpression increased tumour growth and JUP expression in nude mice." (PMID 37328487, 2023). "JUP has previously been implicated in multiple cancers although it is generally found to be a tumour suppressor protein, rather than the oncogenic properties it has in the context of OAC." (PMID 36803948, 2023). "Conversely, FAP-positive tumour cells expressed significantly lower levels of genes encoding epithelial junction proteins (including CDH1, JUP, CTNN1A) epithelial differentiation markers, including several keratins (6B, 7, 17, 19, 23) and mucins (1, 3A, 4, 12), and chemokines (CXCL1-3, 5, 6)." (PMID 35296803, 2022). "Phosphosites from immune system-associated proteins (e.g., IL3RA, PECAM1, PTPN1, SIGLEC7, and JUP) showed an overall higher phosphorylation in tumor tissues than in normal adjacent tissues, suggesting enhanced immune signaling is likely to occur during tumor development." (PMID 33953186, 2021). "Whether JUP acts as a tumor suppressor or an oncogenic protein may depend on differential expression levels of JUP at different stages of tumorigenesis or within distinct molecular subsets of the same tumor entity." (PMID 33533127, 2021).
tumor (continued). "Consistent with our theory, the protein expression of MMP7 and CCND1 were downregulated in a SOX30-overexpressing cell line and xenograft tumors; MMP7 and CCND1 expression were increased significantly in SOX30-overexpressing cells, or tumor tissue after DSP or JUP expression was blocked." (PMID 29855376, 2018). "To define whether desmosomal genes are involved in the antitumor effects of SOX30, we focused on the most differentially expressed desmosomal genes associated with SOX30 and chose the three prominent tumor suppressors DSP, JUP and DSC3." (PMID 29855376, 2018). "In addition, both integrins (ITG) and JUP are located around the cell membrane, and their expression ratio may reflect the tumor stage of SCC." (PMID 34203070, 2021). "While canonical EMT is well-studied in cancer progression, the hEMT state—marked by co-expression of epithelial (e.g., CDH1, IRF6, JUP) and mesenchymal (LAMC2, ITGB4, TGFA) genes—has emerged as a driver that enhances cellular plasticity and tumor metastasis." (PMID 40777467, 2025). "Therefore, whether JUP serves as a tumour suppressor or an oncogenic protein in BLCA is unknown." (PMID 37328487, 2023). "Meanwhile, the GEPIA database showed that JUP, ITGB4, ST3GAL2, ST3GAL5 and B4GALNT1 were higher expressed in tumor samples than in paired normal tissues." (PMID 34402716, 2021). "Then, in UALCAN database, we found JUP and ITGB4 were higher expressed in tumor while ST3GAL5 and ST8SIA1 were lower expressed in tumor." (PMID 34402716, 2021). "We also examined the expression levels of JUP (gene for plakoglobin), CD44, and PAK2 in CTCcl+ vs. CTCcl− TNBC PDX models as they were reported to have a role in tumor cell aggregation/CTCcl formation and subsequent metastasis." (PMID 31652963, 2019). "This asRNA is located in the locus containing genes JUP, FKBP10, HAP1, LEPREL4 and EIF1 upregulated in HPV16+ tumours." (PMID 29263803, 2016). "Specifically, the tumor-suppressive role of miR-195-5p in CRC has been demonstrated, revealing it as a critical regulator of multiple cellular processes and identifying γ-catenin (JUP), keratin 23 (KRT23), and pinin (PNN) as its major downstream targets." (PMID 40871106, 2025). "The results indicated that the upregulated hub genes COL7A1 and JUP were negatively correlated with tumor-infiltrating monocytes, while the downregulated hub genes MSLN and CHRDL1 were positively correlated with tumor-infiltrating monocytes, with a p value < 0.05." (PMID 35993054, 2022). "To further investigate whether upregulation of DSP, JUP and DSC3 are necessary for SOX30-medicated tumorigenesis and metastasis in vivo, we utilized a xenograft tumor model using these stable cell lines." (PMID 29855376, 2018). "TMEM108 and C3orf47 were positively correlated with tumor grade and eight genes, including LAD1, TIF1, FGF11, carbonic anhydrase 12 (CA12), G protein subunit α15 (GNA15), junction plakoglobin (JUP), plakophilin 1 (PKP1) and PPARD, were negatively correlated with the tumor grade of ESCC patients." (PMID 28904855, 2017). "However, a closer look at the respective genes reveals that many of them (SFRP5, WISP3, DKK4, FRZB and JUP) are antagonists of the 'WNT-beta catenin' pathway, thus exerting a tumor suppressor role in normal conditions." (PMID 19327144, 2009). "However, the downstream signaling pathway of these desmosomal genes in regulating tumor progression is not entirely clear, except for the three canonical tumor suppressor desmoplakin (DSP), junction plakoglobin (JUP) and desmocollin 3 (DSC3)." (PMID 29855376, 2018).